SPRTN (SprT-like N-terminal domain)
Diseases named in the same sentence as SPRTN in open-access papers:
SPRTN is named in the same sentence as 19 diseases in open-access papers, as found by Europe PMC text mining. Sharing a sentence is not in itself a finding about the gene and the disease. The quoted sentences say what the papers report.
hepatocellular carcinoma (11 papers, 2015 to 2024). A malignant tumor that arises from hepatocytes. "Germline mutations in SPRTN have been seen in patients with Ruijis-Aalfs syndrome which is characterized by increased risk of hepatocellular carcinoma." (PMID 39328207, 2024). "Mutations within SPRTN have been shown to be the cause of Ruijs-Aalfs syndrome, a genetic disorder that leads to genomic instability, early-onset hepatocellular carcinoma, and progeria." (PMID 39328207, 2024). "Cells derived from patients with SPRTN mutations elicit genomic instability and people afflicted with this syndrome developed hepatocellular carcinoma." (PMID 27852435, 2016). "Recently, three patients showing early onset hepatocellular carcinomas and progeroid syndrome have been found to carry a mutation in SPRTN." (PMID 27379156, 2016). "Previous studies have also linked SPRTN to premature aging and hepatocellular carcinoma." (PMID 39109335, 2024). "Thus, SPRTN mutation result in genome instability, early-onset hepatocellular carcinoma and progeria underscoring the importance of both N-terminal SprT domain and C-terminal protein-protein interaction domains of SPRTN in SPRTN function." (PMID 35782873, 2022). "Mutations of SPRTN could lead to the early onset of hepatocellular carcinoma and genomic instability." (PMID 33668039, 2021). "SPRTN could decrease DNA replication stress in DNA replication and G2/M-checkpoint regulation and the mutation of SPRTN could cause early onset of hepatocellular carcinoma." (PMID 29100313, 2017). "Taken together, these results provide a molecular explanation for the defects associated with Ruijs-Aalfs syndrome and shed light on how mutations in SPRTN can contribute to segmental progeroid syndrome, genome instability and hepatocellular carcinoma development." (PMID 27852435, 2016). "Therefore, given that Spartan plays a significant role in DNA stability by being responsible for DPC repair throughout DNA replication, pathogenic variants in the SPRTN gene affect DNA repair and are associated with hepatocellular carcinoma and premature aging, such as in RJALS." (PMID 36354755, 2022). "It remains to be seen if aldehyde levels are higher in SPRTN deficient cells or if SPRTN deficiency in conjunction with non-alcoholic fatty liver disease cause increased DPC formation and hepatocellular carcinoma development." (PMID 39328207, 2024). "Biallelic mutations in SPRTN cause Ruijs-Aalfs (RJALS) syndrome, characterized by hepatocellular carcinoma and segmental progeria, indicating the critical role for SPRTN and DPC repair pathway in genome maintenance." (PMID 35782873, 2022). "Interestingly, DPC accumulation in the liver is particularly oncogenic as it has been found that patients lacking the fundamental DNA-protein crosslink repair metalloprotease SPRTN/DVC1 develop very early onset aggressive hepatocellular carcinomas." (PMID 30088263, 2018). "A SPRTN deficiency has been linked with a new progeroid syndrome with propensity to develop early onset hepatocellular carcinomas, but it is still not clear whether this phenotype is directly linked with its proposed control of polη." (PMID 27379156, 2016). "In the absence of SPRTN, these persistent DPCs lead to DNA damage and mutagenesis, likely contributing to the development of hepatocellular carcinoma in patients with Ruijis-Aalfs syndrome." (PMID 39328207, 2024).
Ruijs-Aalfs syndrome (11 papers, 2016 to 2025). "A hereditary premature aging disorder known as Ruijs-Aalfs syndrome is characterized by mutant alleles of the SPRTN protease implicated in DPC digestion." (PMID 38777831, 2024). "The SPRTN gene, mutated in the premature aging disorder Ruijs-Aalfs Syndrome, encodes a PCNA-interacting protein that operates in DNA damage tolerance." (PMID 38777831, 2024). "While loss of SPRTN is lethal in mammalian cells, hypomorphic variants cause Ruijs-Aalfs syndrome, which is characterized by premature ageing and early-onset hepatocellular carcinoma." (PMID 36681662, 2023). "Using PxP, we investigate DPC repair in cells genetically-engineered to express variants of the SPRTN protease that cause premature ageing and early-onset liver cancer in Ruijs-Aalfs syndrome patients." (PMID 36681662, 2023). "We find that this global-genome DPC cleavage by SPRTN requires SUMO-targeted ubiquitylation of the DPC, occurs independent of proteasomal degradation, and is defective in cells expressing Ruijs-Aalfs syndrome-associated SPRTN variants." (PMID 36681662, 2023). "The resulting mutant cells express a SPRTN-ΔC variant, which is highly reminiscent of the truncated SPRTN variants observed in Ruijs-Aalfs syndrome patients." (PMID 36681662, 2023). "We conclude that SPRTN-ΔUBZ fully phenocopies the effect of Ruijs-Aalfs syndrome patient variants, suggesting that loss of ubiquitin-binding is the key defect of SPRTN-ΔC." (PMID 36681662, 2023). "Ruijs-Aalfs syndrome is caused by partial loss-of-function SPRTN mutations and is characterized by progeroid features and early onset hepatocellular carcinomas." (PMID 36681662, 2023). "Lastly, we monitored SUMOylation in SPRTN-mutated cells from a Ruijs-Aalfs syndrome (RJALS) patient." (PMID 34879279, 2021). "In humans, mutations in SPRTN that compromise its protease activity cause Ruijs-Aalfs syndrome (RJALS), which is characterized by genomic instability, premature aging, and hepatocellular carcinoma." (PMID 30595436, 2019). "Here we have focused on elucidating the molecular mechanisms that lead to genomic instability in cells from patients with Ruijs-Aalfs syndrome that have underlying mutations in the SPRTN gene." (PMID 27852435, 2016). "Our data also provide a molecular explanation on how SPRTN deficiency causes the premature aging and cancer predisposition disorder Ruijs-Aalfs syndrome." (PMID 27871365, 2016). "Germline mutations of SPRTN are causative for Ruijs-Aalfs syndrome (RJALS), which is characterized by genome instability, premature aging, and early-onset hepatocellular carcinoma." (PMID 27871365, 2016). "Very recently, we identified rare SPRTN germ-line mutations in three patients from two unrelated families afflicted with Ruijs-Aalfs syndrome." (PMID 27852435, 2016). "Replacing key interfacial residues prevents allosteric activation of SPRTN by ubiquitin, leading to genomic instability and cell cycle defects in cells expressing truncated SPRTN variants that cause premature aging and liver cancer in Ruijs-Aalfs syndrome patients." (PMID 40691134, 2025). "Notably, SPRTN knock-out causes early embryonic lethality in mice, and its biallelic mutations or down-regulation cause Ruijs-Aalfs syndrome (RJALS) in humans or RJALS-like phenotype in mice, respectively." (PMID 40685547, 2025). "Moreover, germline mutations in SPRTN, which result in the deletion of the enzyme's C-terminal tail, are causative for Ruijs-Aalfs syndrome (RJALS)." (PMID 33348378, 2021). "Ruijs-Aalfs syndrome is a segmental progeroid syndrome resulting from mutations in the SPRTN gene." (PMID 27852435, 2016). "Our finding that the SPRTN-∆C and SPRTN-Y117C alleles found in Ruijs-Aalfs syndrome patients are hypomorphic is consistent with accelerated aging phenotypes observed in the hypomorphic SPRTN mouse model - linking DPC repair deficiency to segmental progeroid syndrome." (PMID 27852435, 2016).
Ruijs-Aalfs syndrome (continued). "The characterization of Ruijs-Aalfs syndrome has underscored the importance of SPRTN in maintaining genomic stability and the effect of aldehyde-induced DPCs when they cannot be properly repaired." (PMID 39328207, 2024). "To gain further molecular insight into the compromised activities of SPRTN-Y117C and SPRTN-∆C mutant proteins identified in Ruijs-Aalfs syndrome patients, we more closely analyzed the primary amino acid sequence of these mutant proteins." (PMID 27852435, 2016). "Ruijs-Aalfs syndrome (RJALS) patient cells with monogenic and biallelic mutations in SPRTN are hypersensitive to DPC-inducing agents due to a defect in DNA replication fork progression and the inability to eliminate DPCs." (PMID 27871366, 2016). "Collectively, SPRTN is a mammalian protease required for resolving DNA-protein crosslinks in vivo whose function is compromised in Ruijs-Aalfs syndrome patients." (PMID 27852435, 2016). "SPRTN null cells or cells derived from patients with Ruijs-Aalfs syndrome are impaired in the resolution of covalent DPCs in vivo." (PMID 27852435, 2016). "The fact that SPRTN patient variants displayed compromised global-genome DPC repair may explain the defects observed in non-replicative tissues of Ruijs-Aalfs syndrome patients." (PMID 36681662, 2023). "Importantly however, loss of the UBZ domain alone was sufficient to recapitulate the phenotypes of SPRTN-ΔC suggesting that ubiquitin binding is the critical feature lacking in Ruijs-Aalfs syndrome-associated SPRTN variants." (PMID 36681662, 2023). "Having already established that SPRTN-KO cells are sensitive to DPC-inducing drugs and that SPRTN has proteolytic activity both in vivo and in vitro, we asked if cells derived from patients with Ruijs-Aalfs syndrome were also compromised in DPC resolving activity." (PMID 27852435, 2016).
liver cancer (8 papers, 2016 to 2025). An epithelial or non-epithelial malignant neoplasm that arises from the liver. "Our finding was also corroborated in liver cancer cells where the sample with a deleterious mutation in SPRTN carried a much higher gCn→A mutation load than samples with wild-type SPRTN." (PMID 38260495, 2024). "Mutations in SPRTN cause premature ageing and liver cancer in humans and mice; thus, defective DPC repair has great clinical ramifications." (PMID 30170832, 2018). "SPRTN deficiencies in humans and in mice have been linked to elevated liver cancers." (PMID 39707916, 2025). "Cells deficient in SPRTN protease exhibit DPC-induced replication stress and genome instability, manifesting as premature ageing and liver cancer." (PMID 31316063, 2019). "Finally, it is not well understood why reactive aldehydes and SPRTN function are drivers for liver cancer specifically." (PMID 39328207, 2024). "Our results in yeast were further corroborated upon analysis of whole exome sequenced liver cancers, wherein, tumors with defects in ERCC1 and ERCC4 (NER), FANCD2 (ICL repair) or SPRTN (DPC repair) carried a higher gCn→A mutation load than tumors with no deleterious mutations in these genes." (PMID 38260495, 2024). "SPRTN was shown to be involved in the unfolded protein response (UPR) and interacts with GRP78 in HepG2 liver cancer cells." (PMID 39328207, 2024).
progeroid syndrome (6 papers, 2015 to 2022). A group of rare genetic disorders which mimic physiological aging, making affected individuals appear to be older than they are. "Consistently, germline mutations in SPRTN were identified in patients with a progeroid syndrome characterized by genomic instability and susceptibility toward early‐onset hepatocellular carcinoma (Ruijs‐Aalfs Syndrome/RJALS)." (PMID 35349763, 2022). "The discovery of this new progeroid syndrome further stresses the importance of SPRTN, but additional investigation is needed to clarify the mechanism of action of this protein essential for the DDT." (PMID 27379156, 2016).
bladder cancer (2 papers, 2019 to 2021). "This demonstrates that the cleavage product generated by SPRTN is missing the C-terminal of MRE11, similar to the TR-MRE11 form in some bladder cancer cells." (PMID 33558481, 2021). "Similar N-terminal CHK1 fragments were observed on endogenous CHK1 in S-phase but not in G0-phase of the cell cycle in T24 urinary bladder carcinoma cell line or in HEK293 cells over-expressing SPRTN-wt." (PMID 31316063, 2019).
cervical carcinoma (2 papers, 2016 to 2022). A carcinoma arising from either the exocervical squamous epithelium or the endocervical glandular epithelium. "Of TLS genes, increased expression of SPRTN, DTL, POLD1, PCNA, and VCP occurred most often in cervical cancers." (PMID 36266721, 2022).
Fanconi anemia (2 papers, 2016 to 2024). Fanconi anemia (FA) is a hereditary DNA repair disorder characterized by progressive pancytopenia with bone marrow failure, variable congenital malformations and predisposition to develop hematological or solid tumors. "We have found contributions of DSB-repair, BER, Fanconi anemia, SPRTN, and NER, indicating FA can cause a plethora of DNA lesions with pathogenic consequences." (PMID 38894680, 2024). "Indeed, DPC accumulation is neither observed upon inactivation of key NER and HR players nor the Fanconi anemia pathway, suggesting that the SPRTN-dependent DPC repair pathway is the main, specialized pathway for DPC repair in human cells." (PMID 27871366, 2016).
cancer (14 papers, 2016 to 2024). A tumor composed of atypical neoplastic, often pleomorphic cells that invade other tissues. "The Cancer Genome Atlas (TCGA) data reveals that higher SPRTN levels were associated with decreased patient survival rates, and it was elevated in some of cancer types." (PMID 33558481, 2021). "DPC repair requires DPC proteolysis by specialized proteases (such as SPRTN in higher eukaryotes) or the proteasome, and its importance is highlighted by hypomorphic SPRTN mutations causing premature ageing and cancer predisposition in patients with Ruijs–Aalfs syndrome." (PMID 38600235, 2024). "Biallelic mutations in the SPRTN gene cause Ruijs–Aalfs syndrome, a hereditary disease characterized by progeroid features, early cancer development, and hypersensitivity to DNA damage, likely a result of accumulation of unrepaired dead-end topoisomerase 1 complexes." (PMID 29856874, 2018). "Biochemical characterization of SPRTN mutations from RJALS patients shows that RJALS is caused by a defect in SPRTN protease activity, rendering it unable to process DPCs during DNA replication and therefore leading to DNA replication stress, one of the main causes of genome instability and cancer." (PMID 27871366, 2016). "In this review, we will discuss the mechanism of replication-coupled DPC repair, regulation of SPRTN function and its implications in human disease and cancer." (PMID 35782873, 2022). "In contrast, RAD51B, XRCC3 and SPRTN were differentially methylated and also clustered closely together in all three cancer types." (PMID 27683114, 2016). "Defective SPRTN-dependent clearance of DPCs is the molecular mechanism underlying RJALS, and DPCs are contributing to accelerated aging and cancer." (PMID 27871366, 2016). "It is therefore reasonable to speculate that the proteolysis of replication-associated TOP1-DPCs is primarily driven by the UPP in certain cancers such as CRC due to their low SPRTN expression." (PMID 37353483, 2023). "Thus, aberrant retention of USP1 molecule on DNA caused by combined SPRTN and USP1 catalytic inhibition may be effective in further enhancing cytotoxicity of cisplatin and other chemotherapeutics in a variety of cancer cells." (PMID 35365626, 2022). "Hence, interfering with DPC repair by inhibiting SPRTN may represent a potential therapeutic opportunity that could be exploited to sensitize quickly dividing cancer cells to chemotherapy." (PMID 27871365, 2016). "The molecular mechanism of how SPRTN protects genome stability and prevents accelerated aging and cancer is not clear." (PMID 27871366, 2016). "Furthermore, SPRTN levels were not significantly correlated with MRE11 levels and were independent of cancer stage." (PMID 33558481, 2021). "Thus, in the absence of USP11, SPRTN is inactivated by increased auto-proteolysis, which may lead to inefficient SPRTN-mediated DPC repair, generating genomic instability leading to cancer and premature aging." (PMID 33567341, 2021).
tumor (1 paper, 2024). "Therefore, we used this criterion and identified four tumors with mutations in ERCC4, one tumor with mutation in ERCC1, two tumors with mutations in FANCD2 of which one also had a mutation in ERCC4 and one sample with a mutation in SPRTN." (PMID 38260495, 2024).
SPRTN also shares sentences with these, for which no sentence is quoted: acquired lipodystrophy (1 paper); anemia (1); atransferrinemia (1); gracile bone dysplasia (1); hemochromatosis (1); lung squamous cell carcinoma (1); multiple lipomatosis (1); non-alcoholic fatty liver disease (1); pediatric germ cell tumors (1); premature aging syndrome (1).